MYO5A (myosin VA)
Diseases named in the same sentence as MYO5A in open-access papers (continued):
Sharing a sentence is not in itself a finding about the gene and the disease.
tumor (16 papers, 2015 to 2025). "MYO5A and survivin were implicated in epithelial-mesenchymal transition and tumor motility, and VEGF promoted angiogenesis." (PMID 41206839, 2025). "We used wound-healing migration assay to explore the association between myosin Va and tumor cell migration, and used CCK-8-based cell counting to find out its role in cell viability and proliferation." (PMID 28903372, 2017). "In addition, a novel somatic nonsynonymous mutation in isoform MYO5A (NP_000250.3: p.E926G) was discovered in a PCC tumor sample of our data set." (PMID 32511227, 2020). "To augment these results, we employed gene set variation analysis (GSVA) using gene expression data from TISIDB platform to investigate the correlation of MYO5A with tumor infiltrating lymphocytes (TILs) in HNSC." (PMID 38129784, 2023). "In KEGG analysis results, we noticed that MYO1B, MYO5A, and MYO10 associated DEGs were enriched in PI3K-Akt signaling, focal adhesion process, and ECM-receptor interaction which were all related to tumor metastasis." (PMID 35478939, 2022). "MYO5A is a key component of the myosin V family, which participates in transport vesicle formation, protein transcription, and tumor progression." (PMID 35957868, 2022). "Mechanistically, forced (over)expression of LINC01980 in ESCC cell lines has been shown to promote Myosin-Va (MYO5A) expression by inhibiting miR-190a-5p, resulting in enhanced tumor cell proliferation and EMT." (PMID 34898376, 2021). "In conclusion, this study demonstrates that a high expression of MYO5A, PLTP, or TPP1 is associated with tumor progress and poor prognosis in GC patients." (PMID 32735728, 2020). "Tumor samples showed an increased expression of myosin Va, abnormal actin and myosin Va distribution." (PMID 28903372, 2017). "In this research, we use siRNA knock-down to explore the specific detailed functions of myosin Va during tumor cell mitosis." (PMID 28903372, 2017). "Our results suggest that myosin Va plays essential roles in maintaining normal mitosis, enhancing tumor cell motility and viability, and these properties are the hallmark of tumor progression and metastasis development." (PMID 28903372, 2017). "The strong co-localization between myosin Va and nucleus in tumor cells implied the special functions of myosin Va during tumorigenesis, and these phenomena were in accordance with the concept of ‘chromomyosin’ presented in our former review." (PMID 28903372, 2017). "The different distribution patterns of myosin Va and actin-based microfilament between normal and tumor tissue suggest its functional role in tumor progression." (PMID 28903372, 2017). "The strong co-localization between myosin Va and nucleus in tumor cells imply the myosin Va's special functions during tumorigenesis, which are in accordance with the concept of ‘chromomyosin’ put forward in our former review." (PMID 28903372, 2017). "The strong co-localization between myosin Va and nucleus in tumor cells implies the special functions of myosin Va during tumorigenesis, and these phenomena are in accordance with the concept of ‘chromomyosin’." (PMID 28903372, 2017). "In this study, we find that the expression level of myosin Va in tumor cell nucleus is significantly higher than that in normal cell nucleus." (PMID 28903372, 2017). "As a result, after decreasing the myosin Va's expression in Hela cells, the tumor cells’ motility and viability were significantly inhibited." (PMID 28903372, 2017). "Bcl-xL also affects tumor cell migration and invasion, and can be mediated by myosin Va to promote islet tumor cell motility." (PMID 28903372, 2017). "CCK-8 assay showed a strong relationship between myosin Va knock down and the inhibition of tumor cell proliferation." (PMID 28903372, 2017). "Increasing number of research showed the relationship of myosin Va in cell migration, and tumor invasion." (PMID 28903372, 2017). "The upregulation of myosin VA by Snail was involved in tumor cell migration and metastasis." (PMID 36846347, 2023).
tumor (continued). "This study will help us to understand more about the functions of myosin Va, especially during tumorigenesis, and the main data may help doctors to perform accurate oncodiagnosis and anti-tumor therapies." (PMID 28903372, 2017). "The myosin Va-knock down tumor cells had a slower proliferation speed." (PMID 28903372, 2017). "Testicular tumor showed a higher expression of myosin Va protein than normal testis." (PMID 28903372, 2017). "The antagonistic effects between myosin Va and Vb may regulate the physiological processes of tumor cells." (PMID 28903372, 2017). "In addition, Hela cell line is used to analyze the specific functions of myosin Va during tumor progression, including abnormal cell mitosis, tumor cell proliferation and migration." (PMID 28903372, 2017). "However, in the tumor tissue, the gray values of three dyeing displayed a random model, which showed that myosin Va and actin were randomly distributed in the whole cell." (PMID 28903372, 2017). "More evidence remains to be found for the involvement of myosin Va that then could be useful for future technologies in tumor diagnosis and anti-tumor treatments." (PMID 28903372, 2017). "In tumor cells, myosin Va has a higher expression level than normal cells." (PMID 28903372, 2017). "When myosin Vb is down-regulated; the inactivation of myosin Va may inhibit proliferation, invasion, and motility of tumor cells, whereas myosin Vb could promote these activities." (PMID 28903372, 2017). "However, most of the research pays close attention to the functions of myosin II and VI, and there are few studies exploring the specific roles myosin Va in tumor formation." (PMID 28903372, 2017). "The upregulation of myosin Va in tumor tissue will be important to determine which roles myosin Va may play during tumorigenesis." (PMID 28903372, 2017). "We intend to examine the role of myosin Va in mitosis, tumor cell migration, and proliferation." (PMID 28903372, 2017). "However, in our study, a different distribution of myosin Va presents in the tumor cells." (PMID 28903372, 2017). "Myosin Va could effectively enhance tumor cell motility and viability." (PMID 28903372, 2017). "MYO5A’s interaction with EMT markers such as Snail and Akt further supports its role in facilitating tumor cell motility and metastasis." (PMID 41206839, 2025). "In high MYO5A expression HNSC, there was a low count of tumor infiltrating lymphocytes (TIL), including activated CD4+ T cells, CD8+ T cells, and B cells." (PMID 38129784, 2023). "Western blotting confirmed that protein expression of MYO5A, PLTP, and TPP1 was higher in tumor tissue than in normal tissue specimens." (PMID 32735728, 2020). "RT–PCR confirmed higher expression of MYO5A, PLTP, PALM2‐AKAP2, and TPP1 in tumor tissue than in normal tissue specimens." (PMID 32735728, 2020). "Conjoint analysis of the expression pattern and prognosis roles of hub genes demonstrated the oncogenic effect of EGFR and tumor suppressive effect of PPP3CB and MYO5A in GBM." (PMID 30971889, 2019). "In conclusion, this manuscript provided comprehensive analyses about the expression and function of MYOs in HNSCC, suggested MYO1B, MYO5A, and MYO10 as potential prognostic biomarkers in HNSCC, and revealed the potential novel roles of MYO1B, MYO5A, and MYO10 in tumor immune microenvironment." (PMID 35478939, 2022). "We further observed an overall negative association between NME4 and tumor invasion markers like genes encoding matrix-degrading proteases (MMP7, ADAM17) and actin cytoskeleton remodelers (ROCK1, ROCK2, LIMK2, CFL2, MYO5A)." (PMID 34674701, 2021). "Furthermore, analyses of hub genes' prognostic roles demonstrated significant oncogenic effect of EGFR and tumor suppressive effect of PPP3CB and MYO5A in GBM." (PMID 30971889, 2019). "Opposite to myosin Va, myosin Vb is another member of the class V of unconventional, dimeric nonfilamentous myosins, whose inactivation accelerates tumor cell migration and invasion." (PMID 28903372, 2017).
tumor (continued). "Furthermore, the protein levels of MYO1B, MYO5A, MYO5C, and MYO10 in HNSCC tumor tissues and normal tissues were examined by Human Protein Atlas (HPA) database; consistently, the protein levels of MYO1B and MYO10 were dramatically enhanced in tumor tissues compared with normal tissues." (PMID 35478939, 2022). "Unlike MYO5A, its close homolog, MYO5B, appears to act as a tumor suppressor." (PMID 33670106, 2021). "A previous study pointed that: MYO5A, a deferential expressed gene between invasive and non-invasive NFPA, might be a crucial biomarker for tumor invasiveness." (PMID 33119597, 2020).
neurological disease (5 papers, 2013 to 2023). "Early studies on MYO5A focused on its roles in neuron formation and function, and in neurological disease." (PMID 35288483, 2022). "Initial research of MYO5A concentrated on its role in neurological diseases." (PMID 37667251, 2023).
infection (4 papers, 2012 to 2022). The state of being infected such as from the introduction of a foreign agent such as serum, vaccine, antigenic substance or organism. "We also demonstrate that RV-B14 infection in cells expressing dominant-negative forms of myosin Va and Vb was impaired after virus entry." (PMID 29215055, 2017). "Using immunofluorescent localization and immunoprecipitation, we show that myosin Va co-localized with RV-B14 exclusively after viral entry (15 min post infection) and that myosin Vb was present in the clusters of newly synthesized RNA in infected cells." (PMID 29215055, 2017). "Consistent with that surmise, UL53 primarily localizes to RCs during 50N infection, where we detected more obvious colocalization of UL53 with myosin Va or MCP." (PMID 35336886, 2022). "However, even during WT infection, a subpopulation of UL53 was also evident in the nuclear interior where it colocalized with myosin Va and MCP (as shown by IFA) or capsids (as shown by immunoEM—the IFA studies do not distinguish between capsids and unassembled MCP or partially assembled particles)." (PMID 35336886, 2022). "Notably, we found that in the absence of UL50 following infection with 50N/53F, essentially no UL53 was present at the nuclear rim and there was much more obvious colocalization of nucleoplasmic UL53 with myosin Va or MCP, again consistent with all three proteins localizing at the RC periphery." (PMID 35336886, 2022).
endocrine system disorder (1 paper, 2017). A disease involving the endocrine system. "In the TC vs. WZS group, the highest ranking network, scoring 70, was associated with cellular movement, developmental disorder, and endocrine system disorders; this network comprised myosin VA (MYO5A), miR-145, miR-143, and myosin IB (MYO1B)." (PMID 28045116, 2017).
peripheral nervous system diseases (1 paper, 2021). "We also observed that proteins enriched in GO term of peripheral nervous system disease, including MAP4, MTM1, MYO5A and GDAP1, were significantly increased in T2DM‐MCI patients." (PMID 34528736, 2021).
MYO5A also shares sentences with these, for which no sentence is quoted: coronavirus disease 2019 (2 papers); metastatic colorectal cancer (2); Alzheimer disease (1); Angelman syndrome (1); autism (1); bladder cancer (1); Cerebellar atrophy (1); ciliopathies (1); deafness (1); E. coli infection (1); endometriosis (1); Epileptic encephalopathy (1); esophageal carcinoma (1); gastric cancer (1); gastroparesis (1); Genetic diseases (1); Griscelli syndrome type 2 (1); Griscelli syndrome type 3 (1); heart disease (1); liver cancer (1); Menkes syndrome (1); movement disorder (1); mucormycosis (1); myocardial infarction (1); neuroblastoma (1); oculocutaneous albinism type 1 (1); overactive bladder (1); partial albinism (1); pituitary adenoma (1); progressive neurodegenerative disorder (1).
A further 5 diseases each share a sentence with MYO5A in 1 paper.